NRP1 (neuropilin 1)
Diseases named in the same sentence as NRP1 in open-access papers (continued):
Sharing a sentence is not in itself a finding about the gene and the disease.
cancer (continued). "NRP1 is often studied in the context of tumorigenesis as it is a receptor for vascular endothelial growth factor (VEGF) and contributes to the cancer hallmarks of angiogenesis, invasion and metastasis." (PMID 34025658, 2021). "The prognostic relationship between NRP1 and TMPRSS2 expression level and cancers were further confirmed by analysis with GEPIA." (PMID 34168096, 2021). "As an unidentified immune checkpoint in T cells, blocking Neuropilin-1 (NRP1) can improve immunotherapy and prevent cancer recurrence." (PMID 33987449, 2021). "Vascular endothelial growth factor (VEGF), including its variant VEGF165, in the microenvironment acts through an isoform-specific receptor, neuropilin-1 (NRP1), to attract the movement of cancer cells and is similar to neutrophil chemoattractant movements." (PMID 32139668, 2020). "In immune cells that are generally known to have anti-cancer effects, such as NK cells, CD8+ T cells, and B cells, NRP1 expression also had a weak or moderate positive correlation with their marker gene expression." (PMID 32408477, 2020). "Particularly, SPARC and SPP1 expression were positively correlated to DC-related markers CD86, NRP1, and inhibitory checkpoint markers including LAIR1, HAVCR2, and PDCDLG2 in most cancer types." (PMID 33240930, 2020). "STC1, involved in various cancer-related signaling pathways, induces VEGF expression in GC cells and NRP1 induces proliferation, migration, and metastasis of GC cells." (PMID 33302481, 2020). "Key among these novel biomarkers are the B7H6 ligand, actin-related protein 2/3 (ARP 2/3), neuropilin-1 (NRP-1), desmocollin 2 (DSC2), anion exchanger 1 (AF1), and cancer-related antigens CA-72-4 and CA-19-9." (PMID 32560392, 2020). "For immune score, PLXND1 showed the highest correlation (r = 0.46) across all cancer types, followed by PLXNC1 (r = 0.39), NRP1 (r = 0.23) and NRP2 (r = 0.15) (p < 0.0001)." (PMID 32640719, 2020). "Blockers for NRP1 interlinked with semaphorin can deactivate VEGF secretion and ultimately suppress cancer development and progression." (PMID 30871059, 2019). "Together, these results demonstrate that blockade of Nrp-1 on CD8+ T cells holds therapeutic potential and provides a strong rational for exploiting Sema and Nrp inhibitors as promising drugs for cancer treatment." (PMID 31350404, 2019). "CP was also fused to a peptide that targets the extracellular domain of NRP1 and this fusion protein (CPL-F, CP-Linker-“Find”) is shown to bind to cultured cancer cells and to inhibit NRP1-dependent angiogenesis as well." (PMID 31652529, 2019). "In this context, our work is a building block, since we now show that Nrp-1 negatively influences CD8 T-cell immunity and responses to anti-PD-1 cancer immunotherapy." (PMID 31350404, 2019). "AGO2-bound miRs are taken up by neuropilin-1 (NRP1) and the internalized miRs remain functional, as they specifically regulate proliferation and migration of cancer cells." (PMID 31766495, 2019). "Therefore, targeting NRP1 could serve to counteract immune suppressive mechanisms for cancer therapy; moreover, the analysis of its expression levels could provide a predictive marker of responsiveness to immunotherapy to be validated in future clinical trials." (PMID 31027288, 2019). "Cancer cells of solid tumors express varying levels of VEGFR1, but hardly VEGFR2 and -3, which is why they probably bind VEGF-A mainly via NRP1." (PMID 30717262, 2019). "Neuropilin-1 (NRP1), a TGF-β co-receptor expressed on the membrane of cancer cells, is known to enhance the canonical SMAD2/3 signaling in response to TGF-β." (PMID 31202261, 2019). "We conclude that Nrp-1 is an immune checkpoint that negatively regulates antitumour CD8+ T-cell immunity, and is thus a promising target for combination cancer immunotherapies." (PMID 31350404, 2019).
cancer (continued). "In particular, the VEGF receptor (VEGFR) isoform, neuropilin-1 (NRP1), participates in an autocrine VEGF-dependent signaling mechanism that promotes cancer cell migration." (PMID 29100316, 2017). "Neuropilin-1 (NRP-1) is a transmembrane glycoprotein participating in the growth and metastasis of cancer cells as multifunctional co-receptors by interacting with the signaling pathways." (PMID 26795388, 2016). "NRP-1 interacts with EGFR and promotes its signaling cascade elicited upon EGF stimulation in cancer cells." (PMID 26795388, 2016). "Double IHC indicated that 95.8% of DC-SIGN+ AMs co-expressed NRP-1 and 94.9% for NRP-2, in lung tissue adjacent to the cancer margin." (PMID 26900851, 2016). "Comparison of neuropilin-1 (NRP-1) and neuropilin-2 (NRP-2) expression in alveolar macrophages and interstitial macrophages in lung tissue remote to the cancer nest (physiologically normal lung) (n = 5)." (PMID 26900851, 2016). "By in situ-PCR, NRP-1 and NRP-2 mRNAs were observed in AMs in lung tissue remote to the cancer nest by coloration with Vulcan fast red stain." (PMID 26900851, 2016). "Neuropilin 1 (NRP1) is a single-pass transmembrane protein playing important roles in development, angiogenesis, immunity and cancer." (PMID 27863391, 2016). "NRP1 is a co-receptor for vascular endothelial growth factor (VEGF), and is an anti-angiogenic target in malignant tumors." (PMID 27014911, 2016). "NDGA suppresses NRP1 function by downregulating its expression, which leads to attenuated cell motility, cell adhesion to ECM and FAK signaling in cancer cells." (PMID 27863391, 2016). "Taken together, our results show that NDGA inhibits cancer cell migration by blocking cell-ECM interaction and suppressing FAK activation, both of which are resulted from NRP1 suppression by NDGA." (PMID 27863391, 2016). "Along these lines, in cancer cells Nrp1 differentially impacts TGFβ versus bone morphogenetic protein (BMP) signaling via Smads, with RNAi-mediated Nrp1 silencing leading to increased levels of pSmad1/5/8 and diminished levels of pSmad3." (PMID 26586223, 2015). "Hypoxia inducible factor 1, alpha subunit (HIF1A) was downregulated in common in cancer cells, while stromelysin-1 (matrix metallopeptidase 3), vascular endothelial growth factor A (VEGF-A), and neuropilin-1 were upregulated in common in fibroblasts." (PMID 26171396, 2015). "Neuropilin-1 (NRP1) is a transmembrane glycoprotein expressed by endothelial, dendritic, and regulatory T cells, as well as several other normal cell types and malignant tumor cells." (PMID 24999732, 2014). "NRP-1 along with its other family members like NRP-2 is, therefore, considered as a new target for cancer therapy." (PMID 23185562, 2012). "CONCLUSIONS: Our findings demonstrate that by combining competitive occupancy of NRP1 with potent anti-angiogenic signaling, SEMA-PSI-IG-HBD represents a promising therapeutic candidate for the regulation of pathological vascularization in cancer." (PMID 41840432, 2026). "This will be important for the target validation with the identification of gene-sets in correlation with NRP1 and NRP2 which can work as biomarkers for cancer diagnosis and prognosis as therapeutic targets to reprogram TAMs and disrupt their pro-tumorigenic functions." (PMID 40134439, 2025). "Also, NRP1 contributes to TGFβ1‐induced EMT and metastasis in NSCLC by binding directly to the TGFβRII receptor, further illustrating its role in aggressive cancer behaviors." (PMID 39083441, 2025). "Although NRPs have been implicated in cancer progression, the specific roles of each isoform in TAM polarisation through differentially regulated NRP1 and NRP2-associated genes in cancers have not been explored at the single-cell level." (PMID 40134439, 2025). "Furthermore, distinctive mRNA expression patterns for NRP1 and NRP2 were noted across the 19 distinct cancer types." (PMID 40134439, 2025).
cancer (continued). "Our results suggest that the modulation of NRP1 expression by the stiffness can be a feedback loop to promote malignancy in non-tumoral and cancer cells, contingent upon the mechanosensitivity of the cells." (PMID 38903533, 2024). "Neuropilin-1 (NRP-1) is a cell surface receptor involved, inter alia, in the development of axon guidance and also in physiological, as well as pathological angiogenesis processes, including cancer." (PMID 39181965, 2024). "Because originally NRP1 has been established as a key regulator in EC of VEGFA signalling, many approaches have been used to inhibit NRP1 binding to VEGFA as a potential therapeutic target to prevent angiogenesis in cancer and neovascular eye diseases." (PMID 38323651, 2024). "Notably, CD34, IL7R, NRP1, GZMB, FGF7, and ENO2 exhibited significant expression in cancer stem cells, CD4+ memory cells, regulatory T cells, NK cells, fibroblasts, and neurons, respectively." (PMID 38846945, 2024). "In vitro cellular uptake assay demonstrated that the radiotracer specifically binds to NRP-1 positive cancer cells (MDA-MB-231) rather than NRP-1 negative cancer cells (NCI-H1299)." (PMID 39283414, 2024). "Moreover, NRP1 promotes abnormal growth factor signaling in breast cancer, resulting in EMT-related drug resistance and cancer metastasis." (PMID 38977708, 2024). "Our findings reveal, for the first time, a differential regulation of NRP1 driven by substrate stiffness in non-tumoral and cancer cells, alongside varying impacts of stiffness on cell morphology, actin remodeling, and cell migration." (PMID 38903533, 2024). "In this scenario, our hypothesis is that SEMA3F and its receptors NRP1 and NRP2 could contribute to DCIS progression to IDC, affecting cancer epithelial cells." (PMID 39138514, 2024). "Thus, it is important to investigate NRP1 expression regulation via small molecules and the potential role of SARS-CoV-2-infected cancer patients." (PMID 38138098, 2023). "Interestingly, our study suggests that the expression of both NRP1 and NRP2 is negatively correlated with the infiltration of these cells in almost all cancers." (PMID 37190154, 2023). "Cells positive for NRP1 (NRP1med and NRP1hi cells) or IGF1R (IGF1Rmed and IGF1Rhi cells) and cells positive for FXYD3 (FXYD3med and FXYD3hi cells) were more abundant among P3 patient-derived cancer cells than in P6 and P1 patient-derived cells, respectively." (PMID 37966117, 2023). "Cancer cells were sorted using anti-FXYD3 and anti-NRP1 or anti-IGF1R antibodies." (PMID 37966117, 2023). "NRP1 and EGFR were highly expressed in most cancer cells, and this suggests that PRV-LAV may have potential utility in personalized cancer therapy among patients with NRP1/EGFR-overexpressing tumors." (PMID 37891570, 2023). "ETS2 was positively correlated with CD200, NRP1, ICOSLG, and TNFSF15 across several cancers." (PMID 36760475, 2023). "We observed that the cells double-positive for NRP1 and FXYD3 (ancestor-like CSC enriched) were increased by paclitaxel treatment and they were significantly diminished by combined treatment with ouabain in cancer tissues." (PMID 37966117, 2023). "Besides, there was a robust positive relationship between SNAI2 and NRP1, and CD276 in most of the TCGA cancers." (PMID 37251370, 2023). "Neuropilin-1 (NP-1), another immunohistochemical marker used for the grading of some malignant tumors, has not yet been studied in PTC." (PMID 36676734, 2023). "Neuropilin-1 (NRP1) is a novel target and immunomodulator for cancer therapy." (PMID 35281516, 2022). "To identify potential therapeutic targets of those cancers and immune escape, we have collected more than forty representative immune checkpoint genes, including BTLA, CD200, TNFRSF14, NRP1, LAIR1 and so on, and we evaluated the relationship between expression of COL1A1 and immune checkpoint." (PMID 35789341, 2022).
cancer (continued). "The result showed that the mRNA expression of NRP1 is higher than that of ACE2 in almost all the cancer types and matched normal tissues, indicating that NRP1 might facilitate SARS-CoV-2 infection in both healthy people and cancer patients." (PMID 36338984, 2022). "Interaction between Nrp1 and VEGF-A also mediated promotion of cancer cell stemness." (PMID 36203599, 2022). "Interestingly, CD276, NRP1, and TNFSF4 expressions were significantly negatively correlated with SHC1 in various cancers." (PMID 35601500, 2022). "NRP1, a non-tyrosine kinase transmembrane receptor, is highly expressed in many cancers, especially in gastrointestinal cancers, promoting metastasis and proliferation." (PMID 35571014, 2022). "have found that a high proportion of human Tregs expressed Nrp1 in melanoma and neck squamous cell carcinoma (HNSCC) and peripheral blood lymphocyte (PBL) Tregs from these cancer patients also possessed a clear population of Nrp1+ Tregs in contrast to healthy donor PBL Tregs." (PMID 35474948, 2022). "The ability of NRP1 to bind to a variety of ligands and receptors involved in different signaling pathways, such as SEMA 3 or VEGF for example, suggests that NRPs are involved in many physiological and pathophysiological processes, such as cancer." (PMID 34277411, 2021). "Studies comparing baseline NRP1 tissue expression of men and women without cancer or those with various diseases, however, are still lacking." (PMID 34025658, 2021). "As expected, a high level of expression of αvβ3 and NRP‐1 was clearly observed in cancer tissues compared with noncancerous tissues." (PMID 34213835, 2021). "Therefore, in this study, we investigated the expression profile of NRP1 and ACE2 in kidney renal clear cell carcinoma (KIRC) and kidney renal papillary cell carcinoma (KIRP) patients from various cancer databases." (PMID 34698182, 2021). "Another study demonstrated that neuropilin-1 was exclusively present in cancer cells, as opposed to the control samples, and at distinctly higher levels in G2 and G3 than those in G1." (PMID 33671851, 2021). "Additionally, after NRP1 silencing the activity of MAPK signaling and molecular mechanisms of cancer pathways were predicted by KEGG and IPA® pathway analysis and validated using western blot in BC cells." (PMID 34249735, 2021). "In attempts to gain better insights into the role of NRP1 and TMPRSS1 in cancers, the survival curve of cancer patients with differential expression level of NRP1 or TMPRSS2 was analyzed with the Kalpan-Meier plotter, a large database combining information from GEO, EGA and TCGA." (PMID 34168096, 2021). "The ability to control multiple signaling pathways in different cell types may support the pleiotropic functions of NRP-1, sustaining the hypothesis that NRP-1 might represent a suitable target for cancer therapies." (PMID 34359721, 2021). "Neuropilin-1 (NRP-1) acts as a non-tyrosine kinase receptor for several cellular signaling pathways involved in the proliferation and metastasis of cancer cells." (PMID 33912463, 2021). "Silencing of NRP1 reduced FGF2-dependent ERK activation and inhibited cancer cell growth." (PMID 34830951, 2021). "Furthermore, LATS2 expression was positively correlated with the expression of PTPRC, BCL6, NRP1, and THBD in almost all cancers in the TCGA database." (PMID 34699318, 2021). "We identified a novel AGO2/miR-185-3p/NRP1 regulatory axis that modulates EMT and the metastatic capability of CRC cells, which might represent a regulatory process for cancer cell migration and metastasis in general." (PMID 33846300, 2021). "Therefore, the expression profiles of NRP1 and ACE2 in kidney renal clear cell carcinoma (KIRC) and kidney renal papillary cell carcinoma (KIRP) patients from the various cancer databases were investigated along with their impact on patients’ survivability." (PMID 34698182, 2021).
cancer (continued). "As a co-receptor, neuropilin-1 modulates the activity of various ligands such as VEGF, TGF-β, HGF, or semaphorins, which promotes cancer growth, angiogenesis, and metastasis in various types of cancer." (PMID 32388640, 2020). "Besides α5β1 integrin, NRP1 co-interacts EGF with EGFR, and HGF with c-Met, and activates these pathways which participate in the proliferation of cancer cells." (PMID 32560565, 2020). "NRP1 is a non-tyrosine transmembrane glycoprotein that is highly expressed in various malignant tumors such as NPC25 and inhibits angiogenesis, cell proliferation and invasiveness of NPC26." (PMID 31956372, 2020). "Neuropilin-1 (NRP-1) is a cell surface receptor involved in the development of axon guidance and also in physiological, as well as pathological, angiogenesis processes, including cancer." (PMID 32183142, 2020). "NRP-1 is a multifunctional, transmembrane, non-tyrosine kinase surface glycoprotein that has an important role in cancer and immunity." (PMID 33266104, 2020). "Neuropilin-1 helps to bind VEGF to the cell surface and forms a trimeric complex together with VEGF receptor 2 (VEGFR2), which was suggested to act as a potential bridge between cancer cells and endothelial cells." (PMID 32984308, 2020). "Neuropilin 1 (NRP1), which was known to be involved in metastatic process of cancers, was selected." (PMID 32903845, 2020). "The majority of the tested cancer types showed positive correlation between the expression of NRP1, NRP2, PLXNC1 and PLXND1, negative correlation between expression of PLXNB1, and the three scores." (PMID 32640719, 2020). "In addition, we have also reported that Ctx-TPP11 internalization by cancer cells is dependent on NRP1 and that Ctx-TPP11 suppresses active integrin β1-driven signaling through NRP1-coupled internalization of integrin β1." (PMID 32560565, 2020). "Similar to NRP-1, placental growth factor (PlGF) is a member of the VEGF family and known to mediate angiogenesis, with circulating PlGF shown to be a prognostic marker for cancer." (PMID 31106153, 2019). "In turn, NRP1 can complex with EGFR, which is overexpressed and active in many cancer cells." (PMID 30717262, 2019). "Another compound antagonizing VEGF binding to the NRP1 b1 domain is EG3287, which could reduce VEGF-induced cell migration and sensitize cancer cells to chemotherapy." (PMID 31027288, 2019). "Neuropilin-1 (NRP1) is a co-receptor of vascular endothelial growth factor (VEGF) where NRP1 overexpression is reported to promote angiogenesis as well as enhance invasiveness, aggressiveness, and proliferation of cancer cells." (PMID 31547193, 2019). "Likewise, the miR-376a target genes MYC, NRP1 (Neuropilin-1), and PDIA6 (Protein Disulfide Isomerase Family A Member 6) play crucial roles in cancer-related processes." (PMID 31847321, 2019). "NRP1 acts as a co-receptor for several growth factors including VEGF, TGF-β, HGF, FGF and PDGF, and exhibits versatile functions for neuronal axon guidance, angiogenesis and cancer initiation, growth, and metastasis." (PMID 31420553, 2019). "Despite existing anti-cancer therapeutics targeting VEGF and its known modulation by NRP1, there is limited quantitative information on the binding characteristics of specific isoforms at full-length VEGFR2 and NRP1 in living cells." (PMID 30057299, 2018). "Because the expression of VEGF receptors (both VEGF receptor-1 and -2) is almost absent in these cancer cells, the mechanism mainly depends on NRP1." (PMID 29659486, 2018). "Thus, in cancer cells, VEGF-A seems to bind mainly to NRP1 for its signal transduction if VEGF receptor-1 expression is low." (PMID 29659486, 2018). "It would be highly relevant to continue studies of this interaction in a larger cohort of PDAC patients, and also to investigate if the same effect of VEGFR2/NRP1 trans‐complexes can be observed in other cancer types not explored in detail here." (PMID 30027561, 2018).